NAPEPLD (N-acyl phosphatidylethanolamine phospholipase D)
Description:
D-type phospholipase that hydrolyzes N-acyl-phosphatidylethanolamines (NAPEs) to produce bioactive N-acylethanolamines/fatty acid ethanolamides (NAEs/FAEs) and phosphatidic acid. Cleaves the terminal phosphodiester bond of diacyl- and alkenylacyl-NAPEs, primarily playing a role in the generation of long-chain saturated and monounsaturated NAEs in the brain (By similarity). May control NAPE homeostasis in dopaminergic neuron membranes and regulate neuron survival, partly through RAC1 activation (By similarity). As a regulator of lipid metabolism in the adipose tissue, mediates the crosstalk between adipocytes, gut microbiota and immune cells to control body temperature and weight. In particular, regulates energy homeostasis by promoting cold-induced brown or beige adipocyte differentiation program to generate heat from fatty acids and glucose. Has limited D-type phospholipase activity toward N-acyl lyso-NAPEs (By similarity).
Synonyms: NAPE-PLD; C7orf18; FMP30
Tractability: Small molecule: a structure with a bound ligand is known; a high-quality ligand is known. Antibody: UniProt places it where antibodies can reach, with high confidence. PROTAC: ubiquitination databases record sites on it; its protein half-life has been measured; a small molecule that binds it is known.
Target class: Enzyme; Hydrolase
Gene: Protein-coding gene on chromosome 7 (103,099,776 to 103,151,172, reverse strand). Ensembl gene ENSG00000161048.
Subcellular location: Golgi apparatus membrane; Early endosome membrane; Nucleus envelope; Nucleus, nucleoplasm
Subcellular location (Human Protein Atlas): Cytosol
Pathways (Reactome):
Disease: Biosynthesis of A2E, implicated in retinal degradation
Gene Ontology:
Molecular function: bile acid binding; identical protein binding; N-acylphosphatidylethanolamine-specific phospholipase D activity; zinc ion binding; phospholipase activity
Biological process: N-acylphosphatidylethanolamine metabolic process; host-mediated modulation of intestinal microbiota composition; N-acylethanolamine metabolic process; positive regulation of brown fat cell differentiation; positive regulation of inflammatory response; temperature homeostasis; negative regulation of eating behavior; phospholipid metabolic process; response to ethanol; response to isolation stress
Cellular component: early endosome membrane; extracellular exosome; Golgi apparatus; Golgi membrane; nuclear envelope; cytoplasm; early endosome; neuron projection; neuronal cell body; nucleoplasm; photoreceptor outer segment membrane; hippocampal mossy fiber to CA3 synapse; postsynaptic membrane; presynapse; presynaptic membrane; smooth endoplasmic reticulum membrane
Genetic constraint (gnomAD): Loss-of-function variants: 20 observed, 36.27 expected, observed/expected ratio (o/e) 0.55, 90% interval 0.39 to 0.8. The upper end of that interval is the gene's LOEUF score, 0.8, which puts it in group 3 of 6, group 1 being the genes least tolerant of losing a copy. Missense variants: 396 observed, 481.69 expected, observed/expected ratio (o/e) 0.82, 90% interval 0.76 to 0.89. Synonymous variants: 142 observed, 165.72 expected, observed/expected ratio (o/e) 0.86, 90% interval 0.75 to 0.99.
Homologues: Orthologues: chimpanzee NAPEPLD (99% identical), macaque NAPEPLD (98% identical), pig NAPEPLD (93% identical), rat Napepld (91% identical), mouse Napepld (89% identical), rabbit NAPEPLD (89% identical), guinea pig NAPEPLD (88% identical), dog NAPEPLD (86% identical), tropical clawed frog napepld (75% identical), zebrafish napepld (59% identical), Caenorhabditis elegans nape-2 (38% identical), Caenorhabditis elegans nape-1 (37% identical).
Diseases named in the same sentence as NAPEPLD in open-access papers:
NAPEPLD is named in the same sentence as 30 diseases in open-access papers, as found by Europe PMC text mining. Sharing a sentence is not in itself a finding about the gene and the disease. The quoted sentences say what the papers report.
leukoencephalopathies (1 paper, 2018). "The identification of different NAPEPLD variants in dog breeds affected by leukoencephalopathies with heterogeneous pathological features, implicates the NAPEPLD enzyme as important in myelin homeostasis, and suggests a novel candidate gene for myelination disorders in people." (PMID 29643404, 2018).
lymphoma (1 paper, 2014). A malignant (clonal) proliferation of B- lymphocytes or T- lymphocytes which involves the lymph nodes, bone marrow and/or extranodal sites. "MCL has high expression of a key enzyme in the anandamide synthesis, NAPEPLD and mostly low expression of the anandamide metabolizing enzyme FAAH, suggesting that high anandamide levels are favored in this lymphoma subtype." (PMID 25594062, 2014).
melanoma (1 paper, 2025). A malignant, usually aggressive tumor composed of atypical, neoplastic melanocytes. "Likewise, the lower anandamide and overall NAEs levels observed in the melanoma was not changed by JZL184 treatment, indicating that the biosynthesis of NAEs via N-acyl phosphatidylethanolamine phospholipase D (NAPEPLD) rather than hydrolysis by CES1 could be involved." (PMID 39934865, 2025).
ovarian carcinoma (1 paper, 2022). A malignant neoplasm originating from the surface ovarian epithelium. "Inhibition of mammalian mitochondrial glutamate dehydrogenase, human adenylyl cyclase, and N-acyl-phosphatidylethanolamine phospholipase D.Induces apoptosis of ovarian cancer cells.Apoptosis-inducing photosensitizer for keratinocytes." (PMID 35011530, 2022).
prostate carcinoma (1 paper, 2020). A carcinoma that arises from epithelial cells of the prostate gland. "DU-145 prostate cancer cells respond to TNF-α treatment with an increased expression of PTGS2, of COX-2 and of PGE2 production and this is accompanied by a decreased expression of NAPEPLD without change in NAAA or FAAH expression, thereby producing an imbalance in PTGS2/NAPEPLD." (PMID 33172176, 2020).
neurological disease (1 paper, 2018). "Our study describes a canine neurological disease with distinctive pathological features and implicates the NAPEPLD protein as an important enzyme in myelin homeostasis." (PMID 29643404, 2018).
NAPEPLD also shares sentences with these, for which no sentence is quoted: Obesity (10 papers); Hepatic steatosis (3); Anxiety (2); colitis (2); dyslipidemia (2); endometrial carcinoma (2); Glucose intolerance (2); metabolic disorders (2); steatosis (2); tumor (2); anxiety disorder (1); COVID-19 (1); depression (1); endometritis (1); frontotemporal dementia (1); glioma (1); gynecological cancers (1); Hyperglycemia (1); Hyperinsulinemia (1); Hypertension (1); infertile (1); Insulin resistance (1); liver inflammation (1); neuropathy (1).